CCNE1 (cyclin E1)
Diseases named in the same sentence as CCNE1 in open-access papers (continued):
Sharing a sentence is not in itself a finding about the gene and the disease.
tumor (continued). "The CCNE1 amplification identified in Patient #1′s tumor by FoundationOne next-generation sequencing is important in that it encodes the cyclin E1 protein (which regulates G1 to S phase transition) via binding to and activating cyclin-dependent protein kinase 2 (cdk2)." (PMID 26510912, 2015). "Taken together, decreased mir-424 expression and increased levels of MEK1 or cyclin E1 in senile hemangioma may cause abnormal cell proliferation in the tumor." (PMID 21179471, 2010). "Intratumoral Cyclin E1 expression was homogenous in samples from synchronous but anatomically distinct tumour sites." (PMID 42086671, 2026). "The proportion of Cyclin E1-high (H-score ≥ 150) tumours was 31% (8/26) at diagnosis, 42% (10/24) post-NACT, and increased significantly to 61% (23/38) post-PARPi (versus diagnosis; p = 0.024)." (PMID 42086671, 2026). "Our analysis revealed how CCNE1-high epithelial subsets contribute to tumor progression and immune evasion, providing a rationale for the development of histotype-specific therapeutic strategies for selecting patient subsets." (PMID 41331376, 2025). "The data revealed a statistically significant correlation between positive CCNE1 expression and tumor grade (P = 0.002) as well as T infiltrate (P = 0.035)." (PMID 40346052, 2025). "Western blot analysis of tumor tissue protein extracts confirmed downregulation of CCNE1 expression in the shCCNE1 groups." (PMID 40346052, 2025). "In colorectal cancer (CRC) and bladder cancer (BC), METTL3 accelerates the cell cycle of tumor cells by directly promoting the expressions of CCNE1, AF4/FMR2 family member 4 (AFF4), two key regulators of the NF-κB pathway (IKBKB and RELA), and MYC." (PMID 40136363, 2025). "Considering all tumor types, the mean copy number at CCNE1 was significantly higher in BRD4-deletion samples compared to samples without BRD4 deletions (6.7 vs. 3.1; p = 2.6 × 10−8; Wilcoxon rank-sum test)." (PMID 40112818, 2025). "For the second patient, who experienced a confirmed response, the tumor had evidence of a mutation in PPP2R1A and low copy number gain of CCNE1 (estimated <6 copies)." (PMID 40678577, 2025). "Epitomising this dichotomy, tumours with WGD are more likely to possess CCNE1 amplifications enhancing proliferation, but are also more likely to suffer extreme chromothripsis, which appears to impair tumour development." (PMID 40593568, 2025). "Consistently, tumor volumes and weights were significantly decreased in mice injected with CCNE1-knockdown cells." (PMID 40346052, 2025). "Given the heterogeneous response to CCNE1 depletion among tumor types, we examined the impact of INX-315 at low concentrations across a panel of cell lines." (PMID 39924553, 2025). "In vivo data revealed that ANLN knockdown partially reversed the tumor growth-promoting effect of CCNE1 overexpression." (PMID 40346052, 2025). "CCNE1 staining was predominantly localized in the cytoplasm and nucleus-cytoplasm junction of tumor cells, with scarce positive signals detected in matched para-carcinoma tissues." (PMID 40346052, 2025). "CCNE1 overexpression leads to chromosome instability and enhances the proliferation and metastasis of tumor cells." (PMID 40136363, 2025). "MY-14 exhibited favorable cellular selectivity, showing reduced cytotoxicity against the tested CCNE1-low tumor cell line A549 as well as the corresponding lung epithelial cells." (PMID 41007679, 2025). "Mechanistically, we found that ELA2, primarily derived from tumor-associated neutrophils, cleaves full-length cyclin E1 to generate LMW-cyclin E1, which accelerates OS proliferation." (PMID 40959067, 2025). "To validate the digital PCR (dPCR) assay, we first used 17 tumor samples from our previous study (reference 14), in which CCNE1 copy number status had been determined by whole-exome sequencing (WES)." (PMID 41257933, 2025).
tumor (continued). "Our single-cell analysis revealed that although CCNE1 expression was limited, it was concentrated in epithelial cells, reinforcing its role in cell cycle regulation and tumor proliferation." (PMID 41331376, 2025). "CCNE1 expression is also higher in the presence of SV duplications of any type and particularly so in the tumours where ecDNA and BFBs co-occur (fold change relative to simple SV duplication: 2.8 (95% CI: 1.7–4.6), adj." (PMID 40593568, 2025). "In this study, we combined bulk CNA analysis, single-cell transcriptomics, and spatial transcriptomics across > 12,000 gynecological tumor samples to characterize the heterogeneity of CCNE1 amplification." (PMID 41331376, 2025). "For instance, genes such as AURKA, APEX2, CCNE1, and FOXM1 have been reported to be associated with tumor resistance." (PMID 40098976, 2025). "qRT‐PCR results showed that the expression levels of LINC01116, miR‐9‐5p and CCNE1 were significantly higher in LUAD tumour tissues than in the corresponding adjacent tissues, which was consistent with the results of the previous database analysis." (PMID 39648148, 2024). "CCNE1 amplification is a common alteration in multiple tumor types that leads to G1–S-phase checkpoint dysregulation and genomic instability, a key hallmark of cancer." (PMID 38717153, 2024). "The protein expression of AURKB and CCNE1 in tumor tissues from the three treatment groups were confirmed using western blot." (PMID 38713155, 2024). "More analyses on immunotherapy to further reveal the biological properties and roles of CCNE1 in different tumours are needed to provide an important reference for subsequent studies." (PMID 39591374, 2024). "In the current study, we have shown that tumours with cyclin E1 and CDK2 overexpression have a worse PFS and OS." (PMID 38612869, 2024). "In this study, to analyze the genetic pattern of CCNE1, we used different tumor datasets from the TCGA cohort for our study." (PMID 39591374, 2024). "To investigate the correlation between CCNE1 expression and tumor prognosis in different types of tumors, we used TCGA and GEPIA databases for analysis." (PMID 39591374, 2024). "In summary, we found significant CNA differences in CDKN2A, ERBB2, SMAD4, and CCNE1 between pNET and sbNET tumor samples after combined analyses of chromosomal microarrays, RNA sequencing, and fluorescence in situ hybridization data." (PMID 39062773, 2024). "The results confirmed that a significant downregulation of cyclin B1, cyclin D1, and cyclin E1 in four tumor cell lines were stimulated with H9." (PMID 39458945, 2024). "A previous study has shown that CDK2 inhibitor was more sensitive to inhibit CCNE1-expanded tumor cells." (PMID 38338471, 2024). "If CCNE1 is gained, then the tumor has a greater than 80% chance of being from the pancreas but if it is lost or normal, CDKN2A copy-number status should be assessed." (PMID 39062773, 2024). "More and more studies on the role of CCNE1 in tumor tissues have been reported, for example, CCNE1 over-expression in BRCA, BLCA and OV tissues are associated with poor tumor survival, although there are also some opposite results." (PMID 39591374, 2024). "In contrast, two patients still experienced positive clinical outcomes, although they had HRDneg tumor samples with amplifications of KRAS and CCNE1, respectively, typically associated with resistance to PARPi." (PMID 39591206, 2024). "In vitro antitumor tests showed that III-13 significantly inhibited the proliferation of CCNE1-expressing normal and expanded tumor cells, which suggested that III-13 had other possible regulatory pathways." (PMID 38338471, 2024). "Previous studies have suggested that CCNE1 amplification is a potential prognostic factor in certain tumor types." (PMID 38717153, 2024).
tumor (continued). "We demonstrate a significant increase in anti-tumor activity and overall survival compared to monotherapy alone in CCNE1 amplified OVCA and EMCA PDX models using a low dosing strategy justifying further evaluation in the clinic." (PMID 38410486, 2024). "We also showed that cyclin-E1-overexpressing tumours are enriched for genes involved in insulin signalling and release." (PMID 38612869, 2024). "We have also shown the CCNE1-overexpressing tumours are enriched in genes involved in insulin signalling and release." (PMID 38612869, 2024). "Our study found that the abnormal expression of CCNE1 occurred not only in one tumor, but also in a variety of tumor types." (PMID 39591374, 2024). "miR-7 also promotes hepatocellular lipid accumulation and has tumor-suppressive effects in hepatocarcinogenesis through the suppression of the oncogene cyclin E1 (CCNE1,)." (PMID 39591208, 2024). "Increased H3-pS10 expression was also observed in PKMYT1i-ATRi treated CCNE1AMP (KLE and FUOV1) cells but not in CCNE1GAIN (OVCAR8) or CCNE1LOW (WO-20) cells indicating a conserved mechanism-of-action in tumor-derived CCNE1-amplified models." (PMID 38410486, 2024). "Even though ATR activity is crucial in dealing with the low levels of RS in proliferating healthy cells, its activity becomes more important in tumor cells harboring activated oncogenes such as cyclin E (CCNE1), MYC, and RAS." (PMID 38880245, 2024). "INX-315 treatment resulted in tumor growth inhibition of CCNE1-amplified tumors by promoting retinoblastoma protein hypophosphorylation, inducing cell cycle arrest and delaying the onset of CDK4/6 inhibitor resistance in breast cancer." (PMID 38894867, 2024). "The data suggest that cyclin-E1-overexpressing tumours would be suitable to target using a CDK2 inhibitor." (PMID 38612869, 2024). "Amplification of CCNE1 has been identified in diverse tumor types including approximately 12% of esophagogastric cancer (EGC) and 20% of high-grade serous ovarian cancers from The Cancer Genome Atlas (TCGA) analysis." (PMID 38717153, 2024). "For tumours with high CCNE1, 567 genes were expressed more highly and 1029 genes had a lower expression than in the low-CCNE1 tumours, with CCNE1 differentially expressed with a log2 fold change of 3.01 (FDR-p <0.05)." (PMID 38612869, 2024). "Differential gene expression analysis was performed utilising TCGA-OV RNA-Seq data for 379 samples to analyse genes expressed lower or higher in the tumours with low or high levels of CCNE1 or CDK2 (Q1 vs. Q4)." (PMID 38612869, 2024). "One of the differentially expressed genes expressed at a higher level in the CCNE1/CDK2-high tumours was FOXA1 (FDR-p value < 0.05; log2 fold changes of 2.2 and 1.1, respectively)." (PMID 38612869, 2024). "The levels of CCNE1 expression were shown to be significantly associated with tumor grade in UCEC and tumor stage across cancers, including ACC, HNSC, KIRC, KIRP, KICH and LIHC." (PMID 36964635, 2023). "Abnormal expression of CCNE1 activates cyclin-dependent kinase 2 to phosphorylate its substrate, resulting in tumor cell proliferation." (PMID 37404825, 2023). "FBXW7 is a main tumor suppressor due to its ability to control proteasome-mediated degradation of several oncoproteins such as c-Jun, c-Myc, Cyclin E1, mTOR, and Notch1-IC." (PMID 36934104, 2023). "In xenograft animal models harboring CCNE1 amplification or FBXW7 (encode the E3 ubiquitin ligase which degrades CCNE1) loss, RP6306 dramatically inhibited tumor growth either as monotherapy or in combination with gemcitabine." (PMID 37679326, 2023). "It is thought that CCNE1 overexpression results in ineffective DNA replication, premature entry into S-phase, and genomic instability and is essential for tumor cell proliferation." (PMID 36964635, 2023). "The combination of a CDK2i and an AKTi also resulted in tumor regression in CCNE1-amplified cell lines of HGSOC." (PMID 37842243, 2023).
tumor (continued). "This further indicated that CCNE1 acted as an oncogene in a variety of tumors and has the potential to be a indicator of tumor prognosis." (PMID 36964635, 2023). "Various therapies have been proposed specifically for CCNE1-amplified tumours, including WEE1 kinase and CDK2 inhibitors, and proteasome inhibitors." (PMID 38036971, 2023). "By comparing the overall survival (OS) and disease-free survival (DFS) rates of tumor patients with low and high CCNE1 expression, the prognostic significance of CCNE1 expression levels in multiple tumors was investigated." (PMID 36964635, 2023). "In patients with different tumor types, a high mRNA expression level of CCNE1 was related to a poor prognosis." (PMID 36964635, 2023). "In UCEC, the CCNE1 expression level was upregulated in tumor tissues compared with normal tissues in the TCGA cohort." (PMID 36964635, 2023). "We, therefore, conclude that the down-regulation of Il6 through Ccne1-depletion in HSCs is significantly involved in the reduced tumor burden of DEN/CCl4-treated Ccne1ΔHSC mice." (PMID 37620309, 2023). "We, thereby, performed the Kaplan–Meier and log-rank test analyses using the MYC and CCNE1 amplifications that were assessed by either tumor tissue or CSF samples." (PMID 37131253, 2023). "Altogether, our data indicate that Ccne1 expression in HSCs affects the myeloid composition of the tumor environment during hepatocarcinogenesis." (PMID 37620309, 2023). "Using the LinkedOmics portal, we analyzed CCNE1-related genes to investigate the role of the CCNE1 gene in UCEC tumor development." (PMID 36964635, 2023). "CCNE1 functions as a tumor supporter which was related with the poor prognosis of the patients with negative breast cancer." (PMID 35186236, 2022). "Previous studies have also found that ZC3H13 inhibits the Ras-ERK signaling pathway, reduces the expression of Snail, Cyclin D1, and Cyclin E1, and upregulates the expression of occludin and Zo-1, thereby inhibiting tumor progression." (PMID 38024481, 2022). "Further investigations showed that KDM5B accumulated CCNE1 in tumor cells by decreasing the expression of FBXW7, which resulted in the acceleration of G1/S cell cycle phase transition and finally promoted malignant proliferation." (PMID 35428764, 2022). "This implies that CCNE1 expression exhibits variability between the individual tumor cells, but the degree of variability remains similar at all levels of expression." (PMID 35169222, 2022). "Examples of such tumor-specific alterations include ATM loss, Cyclin E1 (CCNE1) amplification, and APOBEC3 expression." (PMID 35458687, 2022). "For example, CCNE1 features a constant level of variation between individual tumor cells in relation to the mean." (PMID 35169222, 2022). "Cyclin D1 and Cyclin E1 are two crucial G1/S transition regulatory factors that are often deregulated and play oncogenic roles in tumor proliferation and progression." (PMID 34975298, 2022). "CCNE1 amplification is frequently present in tumours with competent homologous recombination pathways and has been associated with platinum-based chemotherapy resistance." (PMID 36289203, 2022).
tumor (continued). "The overexpression of miR-7 has the effect of silencing CCNE1, thus promoting the tumor suppressor effects attributed to the expression of the CCNE1 oncogene." (PMID 36012357, 2022). "IHC results in subcutaneous tumor tissues also showed less cyclin E1 and c-MYC expression in INPP5F knockdown group." (PMID 34996491, 2022). "The results indicated that G6PD changed cell cycle dynamics, facilitated cell proliferation, promoted migration in vitro, and enhanced ccRCC tumor growth in vivo, probably by upregulating Cyclin E1 and MMP9." (PMID 34975298, 2022). "Given that we used two methods to infer tumor purity (targeted sequencing and H&E evaluation), it is unlikely that we missed CCNE1-amplified cases due to low tumor content in DNA samples." (PMID 34485660, 2021). "After the tumor palpable point, the si-CCNE1 with atelocollagen and si-control with atelocollagen were administered subcutaneously once per week for two times." (PMID 34070839, 2021). "Consistently, we found that the enhanced expression of the matrix protein collagen type I alpha-1 chain (Col1a1) in tumours compared to the surrounding liver tissue was diminished after inactivation of Ccne1." (PMID 34830835, 2021). "As expected, 16 weeks after inducing Cre, Ccne1 mRNA levels were strongly reduced in tumours of Ccne1−/− mice compared to controls." (PMID 34830835, 2021). "In line with this, CCNE1 expression levels also correlated with histological tumour grades, supporting the important function of CCNE1 for differentiation and malignancy during all stages of HCC progression." (PMID 34830835, 2021). "Ccne1, Ccnd1 and Ccna2 were significantly induced in tumours compared to surrounding liver tissues of Ccne1f/f and Cdk2f/f animals." (PMID 34830835, 2021). "FGFR2 and CCNE1 gene amplifications were detected in single CTCs, tumor tissue, and ccfDNAs in one patient." (PMID 34178989, 2021). "As G1-S transition overactivation occurs in the majority of malignant tumors, inhibitors of CDK4 and cyclin E1 have emerged as candidate drugs for tumor treatment." (PMID 33937074, 2021). "Analysis of HOXA11 expression in the TCGA ACC dataset showed that it significantly correlated with Ki67 expression (P = 0.0023, r = 0.337) the proliferation gene signature (P = 0.00053, r = 0.381) and CCNE1 (P = 0.0010, r = 0.363) expression in these tumours." (PMID 33214683, 2021). "Gene amplifications of CCND1, CDK12, CCNE1, and ERBB2 were identified in patients with low tumor mutational burden." (PMID 34068652, 2021). "Our data show an increase in cell cycle markers in double-mutant male tumours including Ccne1, a gene commonly amplified in ACC and thought to be a disease driver." (PMID 33214683, 2021). "And in-vivo interference of CCNE1 showed a suppressive tumor growth effect on an ARID1A mutant TOV-21G xenograft mouse model." (PMID 34070839, 2021). "These drugs have also been shown to inhibit tumor progression by altering the expression levels of proteins related to cell cycle and apoptosis such as CCNE1, CDK4 and BCL-2, and by inhibiting drug efflux pumps." (PMID 35155562, 2021). "Previous studies have shown that CCNE1 amplification is more frequent in primary platinum-resistant tumours and correlates with a worse prognosis after primary treatment." (PMID 34567247, 2021). "The si-CCNE1 and cisplatin (60 μg/kg) with an atelocollagen group showed a trend of decreasing tumor weight compared with the si-control and cisplatin (60 μg/kg) group (274.3 ± 136.4 vs. 420.6 ± 216.4, p = 0.191)." (PMID 34070839, 2021).